NES (nestin)
Diseases named in the same sentence as NES in open-access papers (continued):
Sharing a sentence is not in itself a finding about the gene and the disease.
epilepsy (8 papers, 2014 to 2025). A brain disorder characterized by episodes of abnormally increased neuronal discharge resulting in transient episodes of sensory or motor neurological dysfunction, or psychic dysfunction. "It’s noteworthy to mention that LIN28A depletion in other brain regions may influence epilepsy-associated cognitive changes, given the use of the Nestin-Cre system in our study." (PMID 38193536, 2024). "Nestin is a specific marker of mature astrocytes and is expressed in reactive astrocytes in some pathological conditions, including epilepsy." (PMID 40809181, 2025). "The majority of cells in epilepsy groups are Nestin-positive, while a few Ki-67-positive cells were observed." (PMID 40809181, 2025). "To investigate roles of LIN28A in epilepsy, we generated Nestin-Cre:Lin28aloxP/loxP (conditional KO [cKO]) and Nestin-Cre:Lin28a+/+ (WT) mice to block LIN28A upregulation in all neuronal lineages after acute seizure." (PMID 38193536, 2024). "Nestin+/MCM2+ were more numerous in epilepsy cases than non‐epilepsy controls (p < .0001); Bipolar/radial glial‐like MCM2+ NEC were present in 56% of surgical epilepsy cases compared with 20% of controls." (PMID 28925561, 2018). "Quantitative studies comparing nestin expression in surgically resected TLE to PM control tissue in culture showed significantly higher levels in epilepsy cases." (PMID 28925561, 2018). "We have also recently identified nestin-positive glial cells in epilepsy cortical and white matter resections as representing a transient proliferative cell population, important in normal brain repair processes." (PMID 25005575, 2014). "Double-labelling immunofluorescent studies further demonstrated the co-localisation of pS6 with nestin, doublecortin, GFAPdelta in populations of small, immature neuroglial cells in a range of epilepsy pathologies." (PMID 25005575, 2014). "However, an increased number of nestin‐positive cells can be seen in response to several pathologic conditions affecting the CNS, as for example inflammation, ischaemia and epilepsy." (PMID 34877779, 2022). "Therefore altered interneuron development in Nestin-cre;E545K may contribute to epilepsy, aberrant interneuron development cannot represent a common mechanism for epilepsy in both models." (PMID 26633882, 2015). "In the six epilepsy PM cases with HS, there was an impression of fewer NEC overall compared with surgical HS, despite strong nestin capillary endothelial labeling." (PMID 28925561, 2018). "Since most of the H1047R mutants were not viable post-weaning, we assessed Nestin-cre;E545K (megalencephalic) and Nestin-creER;E545K (normocephalic) adults for epilepsy phenotypes." (PMID 26633882, 2015).
gastric cancer (8 papers, 2014 to 2025). A primary or metastatic malignant neoplasm involving the stomach. "Statistical analysis revealed that hypoxia-inducible proteins expression was associated with both Oct4 and Nestin expression as well as metastasis patterns in gastric cancer patients." (PMID 25142304, 2014). "In gastric cancer tissues and cell lines, there was a notable upregulation of the neural stem cell marker nestin, while knocking down nestin reduced cell viability, induced apoptosis, downregulated antioxidant enzymes, and suppressed metastasis." (PMID 40507333, 2025). "In this study, DLL4 and Nestin levels were measured in 383 gastric cancer tissue samples by immunohistochemistry, and the clinico‐pathological features of patients assessed." (PMID 27891816, 2017). "Our group also have shown that Nestin is an important stem cell related marker which was expressed in gastric cancer and correlated with a pessimistic prognosis." (PMID 27891816, 2017). "Calcyclin-binding protein was also a member of that functional group, and its expression has been correlated with resistance to chemotherapy in gastric cancer and positively correlated with the expression of nestin (NES) and the prognostic 80-gene expression profiling (GEP80) model in MM." (PMID 27527861, 2016). "Thus, the expression of the stem cell-related proteins Oct4 and Nestin was also observed in gastric cancer patients." (PMID 25142304, 2014). "Interestingly, DLL4 and Nestin levels were tightly associated, suggesting DLL4 may affect GCSPCs through certain mechanisms in gastric cancer progression." (PMID 27891816, 2017). "In order to investigate the correlation between the expression of hypoxia-inducible proteins and the stem cell-related proteins Oct4 and Nestin, we measured HIF-1α, HIF-2α, Oct4, and Nestin expression in 175 gastric cancer tissue samples by immunohistochemical staining." (PMID 25142304, 2014).
hypopituitarism (8 papers, 2010 to 2025). A condition of diminution or cessation of secretion of one or more hormones from the anterior pituitary gland. "The expression of hGH on the nestin-Cre transgene results in aberrant hGH expression in the hypothalamus, and subsequently may cause hypopituitarism, metabolic and behavioral phenotypes in nestin-Cre mice." (PMID 36543864, 2022). "The use of Nestin-Cre control samples is therefore necessary to distinguish real consequences of deletion of the gene under investigation from side effects resulting from Nestin-Cre associated hypopituitarism." (PMID 20625432, 2010). "Here, our results suggest that the phenotype has a hypothalamic origin, because conditional deletion of the gene using Nestin-Cre is sufficient to reproduce the hypopituitarism characterising the null phenotype." (PMID 39325695, 2024). "Other physiological issues in nestin-Cre mice include behavioral abnormalities, hypopituitarism, decreased levels of growth hormone and reduced body weight." (PMID 36543864, 2022). "Similar reduction in weight and body size, attributed to transgene-induced hypopituitarism and dwarfism, has been previously reported for Nestin-Cre transgenic animals." (PMID 30170615, 2018). "Increased hypothalamic GH receptor signaling explains the observed hypopituitarism, reduced growth and metabolic phenotype of Nestin-Cre mice." (PMID 26275221, 2015). "We report here that Nestin-Cre mice are themselves affected by hypopituitarism and this is expected to have physiological consequences." (PMID 20625432, 2010). "The hypopituitarism displayed by Nestin-Cre mice is post-natal and specific to the Pit-1 lineage (GH, PRL and TSH cells)." (PMID 20625432, 2010). "Two recent studies have shown that nestin-cre mice suffer from hypopituitarism and a defect in fear learning, raising the question whether nestin-cre alone accounts for some of the behavioral phenotype observed in the NHE9 cKO31,32." (PMID 29362376, 2018). "We report here that Nestin-Cre mice themselves are affected by mild hypopituitarism." (PMID 20625432, 2010). "Finally, the hypopituitarism displayed by Nestin-Cre mice has implications for using them to study pituitary phenotypes." (PMID 20625432, 2010).
liver cancer (8 papers, 2018 to 2025). An epithelial or non-epithelial malignant neoplasm that arises from the liver. "In addition, Nestin expression was observed to be associated with advanced-stage, metastasis and recurrence in colorectal and liver cancers." (PMID 39687450, 2024). "We further referred the biological functions of the DE proteins quantified by i-FASP to the previous reports, and as many as 45.6% of the differential expressed proteins were reported to be associated with liver cancer, such as nestin (NES), and adenylyl cyclase-associated protein 1 (CAP1)." (PMID 32675193, 2020). "Nestin expression is significantly elevated in drug-resistant liver cancer tissues and cell lines." (PMID 40799240, 2025). "Finally, the authors found that nestin (a protein of the intermediate filaments) was relatively overexpressed in HCC-CC in comparison with other liver cancers, and that nestin+ tumours were characterized by a grim prognosis." (PMID 32224916, 2020). "Nestin promotes the expression, activation, and nuclear translocation of β-catenin, leading to EMT in liver cancer cells." (PMID 40799240, 2025).
oligodendroglioma (8 papers, 2007 to 2025). A well-differentiated (WHO grade II), diffusely infiltrating neuroglial tumor, typically located in the cerebral hemispheres. "The selection for nestin/SMA positive stromal cells under serum monolayer conditions was also consistently observed in human oligodendrogliomas and oligoastrocytomas with IDH mutations." (PMID 24349039, 2013). "In an oligodendroglioma xenograft, host nestin positive cells were found in the subependymal areas where neural stem cells reside, but the vasculature was also positive regardless of proximity to the tumor." (PMID 24349039, 2013). "Oligodendrogliomas exhibit a proneural genetic signature and the OG cells expressed NG2 and PDGFRα; however, they did not express the proneural markers Sox2, CD133, or Olig2 and only expressed low levels of Notch1 and nestin." (PMID 24278309, 2013).
osteosarcoma (8 papers, 2008 to 2022). A usually aggressive malignant bone-forming mesenchymal neoplasm, predominantly affecting adolescents and young adults. "Out of the differentially modulated genes, those implicated in stem cell and osteosarcoma biology, such as PPARG, ETS1, WNT1, WNT5B, SOX2, NANOG, POU5F1, nestin, and ALDH were chosen for further analysis." (PMID 22870217, 2012). "The validity of these results using newly derived osteosarcoma cell lines was clearly confirmed by immunodetection of the strong nestin positivity also in the established Saos-2 cell line that was used as a control osteosarcoma cell line in our study." (PMID 18925963, 2008). "Our work was aimed at a detailed study of nestin expression in osteosarcomas and osteosarcoma-derived cell lines." (PMID 18925963, 2008). "Our results represent the first evidence of nestin expression in osteosarcomas and suggest the possible occurrence of cells with stem-like phenotype in these tumors." (PMID 18925963, 2008). "Our research was primarily focused on the examination of possible nestin expression in osteosarcoma tissue sections using immunohistochemistry." (PMID 18925963, 2008). "Nestin-positive tumor cells were immunohistochemically detected in all of the examined osteosarcomas, but the proportion of these cells that were positively stained as well as the intensity of staining varied." (PMID 18925963, 2008). "Using immunodetection methods, we examined nestin in tumor tissue samples from 18 patients with osteosarcomas." (PMID 18925963, 2008). "The present study was aimed at the examination of nestin in tumor tissue samples taken from patients with osteosarcomas and in cell lines derived from these tumors using immunohistochemistry and immunofluorescence." (PMID 18925963, 2008). "Our results represent the first evidence of nestin expression in osteosarcomas and suggest the possible occurrence of cells with a stem-like phenotype in these tumors." (PMID 18925963, 2008). "Heterogeneous nestin expression is comparable to the variant or no nestin expression in different osteosarcoma patient samples, further supporting the tumor heterogeneity." (PMID 22870217, 2012). "Nevertheless, our research produced the first evidence of nestin expression in the osteosarcomas." (PMID 18925963, 2008). "Three of the established osteosarcoma cell lines were demonstrated to be nestin-positive, and only one cell line showed no expression of nestin; this finding corresponds with the rare occurrence of nestin-positive cells in the respective tumor sample." (PMID 18925963, 2008). "Control Saos-2 osteosarcoma cell line also clearly showed both of nestin and CD133 positivity." (PMID 18925963, 2008). "Our results regarding the co-expression of CD133 and nestin in newly derived osteosarcoma cell lines as well as in the established Saos-2 cell line suggest the presence of cells with CSCs characteristics also in osteosarcomas." (PMID 18925963, 2008). "Immunoreactivity for nestin was examined in four newly derived osteosarcoma cell lines." (PMID 18925963, 2008). "The most important result of our study is the first evidence of nestin expression in osteosarcomas." (PMID 18925963, 2008). "In contrast, MONC-1 cells gave rise to various tumor types, as 3/7 mice developed osteosarcoma with chondrosarcoma components, 1/7 mouse developed a highly malignant Phox2b−/nestin+ undifferentiated tumor, and 3/7 mice developed Phox2b+/Th−/nestin− undifferentiated NB." (PMID 24947326, 2014). "Three of the established osteosarcoma cell lines were demonstrated to be nestin-positive, and only one cell line showed no expression of nestin." (PMID 18925963, 2008). "In addition to expressing CD133, the human osteosarcoma cell lines Saos-2, OSA-1, OSA-2, and OSA-3 also express nestin, a marker for neural stem cells and brain CSCs, suggesting that nestin and CD133 might be used as co-markers for identifying osteosarcoma CSCs." (PMID 20979639, 2010).
pancreatic ductal adenocarcinoma (8 papers, 2012 to 2024). An infiltrating adenocarcinoma that arises from the epithelial cells of the pancreas. "The expression level of Nestin, which is expressed in not only pancreatic progenitor cells but also pancreatic ductal adenocarcinomas, was also higher in iF cells than in iTS-P cells." (PMID 33504014, 2021). "It has been reported that Nestin is expressed in not only pancreatic progenitor cells but also pancreatic ductal adenocarcinomas." (PMID 33504014, 2021). "In the cells of pancreatic ductal adenocarcinoma nestin overexpression, a stem cell marker rises cell motility and results in phenotypic changes, whereas endogenous nestin knockdown decreases cell migration well as cells also retain its epithelial phenotype." (PMID 33291236, 2020). "Previously, we found nestin immunoreactivity within cancer cells in ∼30% of pancreatic ductal adenocarcinoma cases." (PMID 22580387, 2012). "Approximately 30% of pancreatic ductal adenocarcinoma (PDAC) cases show nestin immunoreactivity; nestin expression correlates with perineural invasion and the presence of cancer cells at the tumor resection margins in PDAC." (PMID 22580387, 2012). "Nine relevant core genes using protein–protein interaction analysis as well as nestin (NES)/vascular endothlial growth factor (VEGF) signaling pathway which is highly related to the pathological process of perineural invasion in pancreatic ductal adenocarcinoma were also discovered." (PMID 38454277, 2024). "In addition, WA was reported to exhibit antiangiogenesis activity by binding to the intermediate filaments vimentin and F-actin, as well as nestin, another filament protein that regulates the TGF-β1-induced epithelial–mesenchymal transition in pancreatic ductal adenocarcinoma." (PMID 31319622, 2019).
pulmonary fibrosis (8 papers, 2014 to 2026). Chronic progressive interstitial lung disorder characterized by the replacement of the lung tissue by connective tissue, leading to progressive dyspnea, respiratory failure, or right heart failure. "In contrast, a recent report suggested that nestin-expressing cells are exclusively associated with CD31-negative pulmonary fibroblasts that accelerate TGFβ-mediated pulmonary fibrosis." (PMID 37735673, 2023). "The deficiency of nestin significantly alleviated pulmonary fibrosis in a mouse model." (PMID 36834561, 2023). "In this study, we report a novel function for Nestin: it plays an essential role in driving EV secretion during the progression of pulmonary fibrosis." (PMID 41496459, 2026). "The first markers of pulmonary fibrosis were detected at 48 hours including indolethylamine N-methyltransferase and nestin." (PMID 40665229, 2025). "The decrease in both nestin and Notch3 expression during pulmonary fibrosis was verified using bleomycin-induced pulmonary fibrosis in nestin-GFP mice." (PMID 37735673, 2023). "Our findings in the present study revealed that the reduction in nestin and Notch3 co-expressing lung endothelial cells were involved in the initiation of pulmonary fibrosis." (PMID 37735673, 2023). "To confirm the decrease in nestin-expressing cells during pulmonary fibrosis, we compared nestin expression between lung tissues of bleomycin- or saline-treated wildtype mice with antibody-based detection of nestin-expressing cells." (PMID 37735673, 2023). "A recent study showed induction of nestin expression in proliferative vascular smooth muscle cells and suggested that it plays an active role in vascular remodeling in pulmonary fibrosis." (PMID 30455628, 2018). "Renal and lung fibrosis was characterized by the accumulation of collagen-immunoreactive mesenchymal cells expressing the intermediate filament protein nestin." (PMID 28448522, 2017). "As the functions of the pericyte subtypes differ in skeletal muscle, we examined their role in pulmonary fibrosis in Nestin-GFP/NG2-DsRed mice." (PMID 25376879, 2014). "While targeting nestin holds therapeutic promise for pulmonary fibrosis, its expression in a broad spectrum of progenitor and structural cells—including myofibroblasts, pericytes, and smooth muscle cells—warrants careful consideration of potential systemic and off‐target effects." (PMID 41496459, 2026). "A negative correlation existed between nestin-expressing cell number and amount of lung hydroxyproline obtained from bleomycin-treated nestin-GFP mice on day 21, suggesting an association between decreased nestin-expressing cells and advanced pulmonary fibrosis." (PMID 37735673, 2023). "However, a recent study reported that increased nestin-expressing mesenchymal/CD31− cells promote pulmonary fibrosis by regulating the TGFβ pathway." (PMID 37735673, 2023). "Thus, we aim to explore whether increased EVs levels from myofibroblasts in pulmonary fibrosis were related with nestin and the Rab family in the present study." (PMID 41496459, 2026). "Therefore, targeting nestin expression in lung myofibroblasts may alleviate lung fibrosis and is a promising therapeutic strategy for IPF." (PMID 36834561, 2023). "Using bleomycin-induced pulmonary fibrosis established in nestin-GFP mice, we found that nestin expression was significantly decreased in the lungs at both the mRNA and protein levels during fibrosis." (PMID 37735673, 2023). "By using nestin-GFP mice, we revealed that lung nestin-expressing cells are predominantly in CD31+ endothelial cells and decrease during pulmonary fibrosis." (PMID 37735673, 2023). "Given that nestin promotes myofibroblast activation by recruiting TBC1D15 to inactivate Rab7 and regulating EVs secretion, we next examined the role of Rab7 in the pathogenesis of experimental pulmonary fibrosis in vivo." (PMID 41496459, 2026).
pulmonary fibrosis (continued). "Contrary to previous reports, neither Nes mRNA expression nor nestin-expressing cells were increased during pulmonary fibrosis." (PMID 37735673, 2023). "Regarding the CD45+ or CD45−/CD31− fraction, there was no significant change in nestin-expressing cells during pulmonary fibrosis." (PMID 37735673, 2023). "Although several studies support the relationship between nestin expression and the establishment of fibrosis in multiple organs, the precise mechanisms by which lung nestin-expressing endothelial cells contribute to the pathophysiology of pulmonary fibrosis have not yet been demonstrated." (PMID 37735673, 2023). "Research shows that this marker is present in pathological conditions as well; for example, nestin contributes to progression of pulmonary fibrosis, and hypoxia-induced nestin promotes progression of non-small lung cancer cells by targeting specific transcription factors." (PMID 36649044, 2022).